SUCNR1 (succinate receptor 1)
Diseases named in the same sentence as SUCNR1 in open-access papers (continued):
Sharing a sentence is not in itself a finding about the gene and the disease.
tumor (55 papers, 2017 to 2026). "Lactate activates PKA/cAMP pathways and promotes immunosuppressive tumor-associated macrophages (TAMs), whereas succinate signals through succinate receptor 1 (SUCNR1) to reinforce HIF-1α-dependent transcription and M2-like programming." (PMID 41828519, 2026). "Different teams have demonstrated that succinate-SUCNR1 regulated tumor-associated macrophages and adipose-tissue-resident macrophages M2 type polarization." (PMID 38291510, 2024). "For instance, succinate secreted by lung cancer cells can engage SUCNR1 on macrophages, stimulating their polarization into tumor-associated macrophages (TAMs)." (PMID 39438765, 2024). "Tumor cells can also release succinate extracellularly, where it signals through the succinate receptor (coded by SUCNR1) to promote tumor-associated macrophage polarization as well as cancer cell invasion and metastasis." (PMID 38273844, 2023). "This is because cancer cells release succinate from the TCA cycle into the microenvironment; this is able to accumulate succinate receptor 1 (SUCNR1) and polarize macrophages in the tumor-associated macrophages (TAMs)." (PMID 38139250, 2023). "Our data displayed a distinct association of SUCNR1 with the microbiome signature, tumor immune infiltrates, and immunomodulators in two different RCC subtypes." (PMID 36551549, 2022). "To this end, we used the TISIDB platform to further investigate the association of SUCNR1 with tumor immune infiltration." (PMID 36551549, 2022). "While an earlier study has demonstrated increased IL‐1β production via SUCNR1 signalling, more recent reports propose an anti‐inflammatory role of the succinate‐SUCNR1 axis in tumour‐associated and adipose tissue macrophages." (PMID 33460504, 2021). "The authors suggest that, besides a direct effect on cancer cells, activation of SUCNR1 in macrophages contributes to the metastatic process by inducing a tumor-associated macrophage phenotype that promotes cancer cell migration through a paracrine action." (PMID 33113952, 2020). "Indeed, our study further illustrated a difference in microbiome signature in KIRC and KIRP tumor tissues associated with high expression of SUCNR1." (PMID 36551549, 2022). "While its role in cancer has been poorly studied, SUCNR1 has been proposed as a tumor driver, as succinate-SUCNR1 signaling has been related to epithelial-to-mesenchymal transition, angiogenesis and tumor-associated macrophage polarization." (PMID 33916314, 2021). "We thus hypothesized that a combination of abundant succinate and its receptor SUCNR1 is a unique characteristic of SDHx-mutated tumors, which highly likely contributes to tumor formation, growth, or spread." (PMID 33776908, 2021). "In addition, cancer cells are known to deliver succinate into the cancer microenvironment and consequently trigger SUCNR1 to polarize macrophages into tumor-associated macrophages, thus stimulating cancer cell malignant behaviors, as well as augmenting cancer metastasis." (PMID 36035205, 2022). "Succinate receptor 1 (SUCNR1) is present on the surface of many tumor cells under hypoxia and its activation triggers extracellular succinate uptake in target cells." (PMID 39796781, 2025). "High succinate concentrations in the TME also increase the expression of SUCNR1 on many tumor cells, but CD4+ and CD8+ T cells instead downregulate SUCNR1 in response to succinate exposure, probably owing to its deleterious effects in these cells." (PMID 39796781, 2025). "In CD8 + T lymphocytes, the autocrine engagement of SUCNR1 by succinate is required to sustain anti-tumor cytotoxic activity." (PMID 39438765, 2024). "It is also reported that tumor-derived succinate promoted tumor-associated macrophage (TAM) polarization and IL-6 release via SUCNR1, resulting in cancer metastasis." (PMID 38291510, 2024).
tumor (continued). "But, inhibiting PDH increases pyruvate carboxylase (PC) activity and succinate secretion, which can activate the succinate receptor 1 (SUCNR1) and enhance anti‐tumour cytotoxicity in CD8+ T cells." (PMID 38935536, 2024). "Beyond immune cell interactions, secreted succinate from tumor cells binds to endothelial cell SUCNR-1, activating downstream STAT3-ERK1/2 in a HIF-independent manner and subsequently upregulating VEGF, thereby fostering angiogenesis." (PMID 37867526, 2023). "Succinate, which is produced by tumor cells, activates the succinate receptor SUCNR1 in TAMs and subsequently stimulates PI3K-HIF-1α axis to promote tumor metastasis." (PMID 37367892, 2023). "Genetic deletion of SUCNR-1 results in reduced tumor growth and metastasis, suggesting that tumor-released succinate promotes tumor growth through activation of SUCNR-1." (PMID 37446354, 2023). "Although RCC had a higher SUCNR1 level compared to other cancers, both RCC tumor subtypes had lower SUCNR1 mRNA transcript compared to normal tissues (p < 0.001)." (PMID 36551549, 2022). "Extracellular succinate induces tumor angiogenesis through SUCNR-1-mediated ERK1/2 and STAT3 activation resulting in upregulation of vascular endothelial growth factor (VEGF) expression." (PMID 36344992, 2022). "Meanwhile, tumor-derived succinate also activates SUCNR1 on the membrane of tumor cells to induce cancer cell migration and EMT through the PI3K/HIF-1α pathway." (PMID 36071472, 2022). "Tumor-derived succinate also promotes succinate receptor 1 (SUCNR1)/phosphoinositide 3-kinase (PI3K)/HIF-1α-dependent polarization of peritoneal macrophages in vitro, enhancing macrophage expression of arginase-1." (PMID 34876704, 2022). "In this study, we have highlighted the potential role of the succinate receptor, SUCNR1, in modulating the tumor microenvironment in the RCC subtypes." (PMID 36551549, 2022). "Findings from murine xenograft tumor models support a critical role for succinate/SUCNR-1 in driving cancer metastasis." (PMID 36344992, 2022). "The succinate receptor, SUCNR1, has been attributed to tumor progression, metastasis, and immune response modulation upon its activation via the oncometabolite succinate." (PMID 36551549, 2022). "Our study broadens the perception of the SUCNR1 role, for the first time, as not only cell-specific but also as tumor-specific." (PMID 36551549, 2022). "This further emphasized the divergent role that SUCNR1 specifically plays in altering the tumor immune infiltration dependent on the RCC subtype." (PMID 36551549, 2022). "Cancer cell-derived succinate induces EMT, tumor angiogenesis and matrix metaloprotinase expression via SUCNR-1-mediated signaling and transcriptional pathways as well as epigenetic modification such as hypermethylation." (PMID 36344992, 2022). "Herein, our findings were in accordance with the latter, such that SUCNR1 stimulated the growth and metastasis of CRC cells, which was associated with inhibition of tumor cell autophagy." (PMID 36035205, 2022). "In one noteworthy example, the signalling molecule succinate binds to and activates succinate receptor 1 (SUCNR1) to promote tumour cell proliferation and metastasis." (PMID 35428309, 2022). "The subsequent activation generates pro-tumor TAMs, driven by the SUCNR1-triggered-PI3K—hypoxia inducible factor (HIF)-1α axis." (PMID 35345849, 2022). "Our findings illustrate a significant novel subtype-specific role of SUCNR1 in RCC which potentially modulates tumor immune infiltration and microbiome signature, hence altering the prognosis of cancer patients." (PMID 36551549, 2022). "Succinate accumulates in tumor cells due to the dysfunction of succinate dehydrogenase, and high amounts of succinate released by tumor cells into the TME activates succinate receptor 1 (SUCNR1) expressed on macrophages." (PMID 35345849, 2022).
tumor (continued). "In this in silico study we have unraveled SUCNR1 probable function in altering the tumor microenvironment in RCC patients, using correlation analysis of data displayed in public databases." (PMID 36551549, 2022). "In another study, tumor cell-derived succinate resulted in TAM polarization toward a pro-tumor phenotype through a succinate receptor (SUCNR1) and was dependent on the PI3K/HIF1α signaling pathway that resulted in enhanced metastasis." (PMID 33968034, 2021). "We found that infiltrating tumor exhibited robust SUCNR1 protein staining (scores 3+), confirming that the transcriptional regulation of SUCNR1 in the infiltrating tumor is mirrored at the protein level." (PMID 33916314, 2021). "Further roles of SUCNR1 on metastatic spread, immune-modulation and chemotaxis, or tumor angiogenesis, as observed in other tissues, remain to be evaluated in SDHx PPGLs." (PMID 33776908, 2021). "Extracellular succinate further contributes to the migration of macrophages into the tumor site and their differentiation into tumor-promoting cells, by engaging its receptor SUCNR1 on the macrophage-cell surface, which drives the PI3K-HIF-1α pathway." (PMID 34831183, 2021). "In contrast, extracellular succinate stimulates SUCNR1 on the tumor-cell surface furthering tumor proliferation and metastasis." (PMID 34831183, 2021). "The SUCNR1-triggered PI3K–HIF-1α signaling cascade promotes tumor cell migration and invasion." (PMID 40297580, 2025). "Additionally, the activation state of HIF-1α stabilization and SUCNR1 signaling in our tumor model needs direct examination." (PMID 41568043, 2025). "Moreover, tumor-derived succinate triggers the reprogramming of peritoneal macrophages and enhances their migration via the succinate receptor 1 (SUCNR1)/PI3K/HIF-1α signaling pathway, ultimately increasing Arg1 expression and promoting arginine metabolism." (PMID 38185636, 2024). "In addition, succinic acid secretion in the tumor microenvironment and autocrine activation of succinate receptor 1 (SUCNR1) play an important role in maintaining the cytotoxicity of CD8+ T cells." (PMID 38835341, 2024). "Furthermore, in vitro and in vivo studies have shown that tumour-derived succinate in the TME can activate SUCNR1, leading to the polarization of macrophages into TAMs." (PMID 37491279, 2023). "The tumour-derived soluble molecule succinate activates succinate receptor 1 (SUCNR1) signalling to polarize macrophages into TAMs and promote tumour cell migration and invasion as well as metastasis by the SUCNR1-triggered PI3K-HIF-1α axis." (PMID 37491279, 2023). "All in all, these findings indicated SUCNR1 could induce the malignant features of CRC cells via suppression of tumor cell autophagy." (PMID 36035205, 2022). "Similarly, elevated succinate was measured in human gastric cancer tissues in comparison to paracancerous tissues, where the succinate–SUCNR1 axis induced tumor angiogenesis via regulation of ERK1/2 and STAT3 signaling." (PMID 36551845, 2022). "This study provides the conceptual basis for the involvement of SUCNR1 in the tumor microenvironment, which may be applied to different types of cancers." (PMID 36551549, 2022). "So far, most studies on succinate in inflammatory response and other physiologic and pathological circumstances including in the muscle in response to exercise training and in the tumor microenvironment have focused on its receptor SUCNR1 expressed on various cell surfaces." (PMID 35309330, 2022). "Targeting the succinate/SUCNR1 axis between tumor cells and TAMs may be a prospective anti-tumor method in the future." (PMID 36497444, 2022). "The mucosa adjacent to the infiltrating tumor showed a heterogenous pattern of SUCNR1 expression." (PMID 33916314, 2021). "Data on SUCNR1 in cancer are scarce; however, it has been proposed that it might play a key role in tumor progression of some carcinomas." (PMID 33916314, 2021). "Involvement of SUCNR1 in tumor angiogenesis has also been proposed." (PMID 33776908, 2021).
tumor (continued). "Moreover, the most recent evidence has indicated that tumor-released succinate can activate succinate receptor 1 (SUCNR1) signaling to polarize TAMs toward tumor-supporting phenotypes through a SUCNR1-activated PI3K/HIF-1α axis." (PMID 34603327, 2021). "However, the expression pattern of SUCNR1 in cancers and its role in tumor immunity remain largely elusive." (PMID 33062639, 2020). "However, the role of SUCNR1 in regulating tumor immune cell infiltration is unclear." (PMID 33062639, 2020). "Stromal cell activation of SUCNR1 upregulates VEGF production through STAT3 and Erk1/2 signaling to increase vascularization of the tumor." (PMID 39796781, 2025). "Paradoxically, in the TME, tumor-derived succinate becomes protumorigenic, CRC-secreted succinate recruits macrophages via SUCNR1 and drives TAM polarization through PI3K/AKT and HIF-1α activation." (PMID 41488637, 2025). "While High concentrations of succinate in the tumor microenvironment are taken up by T cells, suppressing glucose flux through the TCA cycle, this, in conjunction with SUCNR1 signaling, inhibits T cell functions." (PMID 41488637, 2025). "Top hits include changes in transcriptional regulation (ZNF385B, SNORA65), tumour microenvironment (COL1A2, COL3A1), and metastatic processes (UCHL1, SUCNR1, THY1)." (PMID 40890143, 2025). "The activation of SUCNR-1 also leads to upregulation of VEGF expression through the activation of ERK1/2 and STAT3, inducing tumor angiogenesis." (PMID 38185636, 2024). "Succinate in the tumor microenvironment (TME) acts in a paracrine manner to enhance cancer cell migration and induce EMT through interaction with SUCNR-1 and the downstream PI-3K/Akt signaling pathway." (PMID 37446354, 2023). "Extracellular succinate, upon binding to succinate receptor-1 (SUCNR-1), activates several oncogenic signaling molecules, such as ERK1/2, Akt, and AMPK, thereby enhancing tumor cell invasion and metastasis." (PMID 37867526, 2023). "Collectively, these studies demonstrate that succinate is a critical regulator of tumor progression and angiogenesis and shed lights on SDH, HIF1α and SUCNR1 as valid targets to manipulate angiogenesis in cancer." (PMID 36551845, 2022). "We found higher SUCNR1 and SDHA expression in tumor tissue from patients with poor locoregional control." (PMID 33916314, 2021). "Although the initial CCM screen evaluated associations with a gene signature of immune activity, including TLS formation, the emerging CCMs covered genes that are expressed by tumor cells (e.g., RSAD2, CMPK2) and stromal fibroblasts (e.g., SUCNR1) as well as immune cells (e.g., POU2F2)." (PMID 40723216, 2025). "Importantly, we show that INHBA maintains mitochondrial SLC25A10 stability, thereby activating the succinate/SUCNR1 axis and the mtGSH/GPX4 axis to promote tumor malignancy." (PMID 41449244, 2025). "We hypothesize that JFAD’s anti-tumor effects may partly result from its regulation of succinate levels, affecting HIF-1α and SUCNR1 signaling pathways." (PMID 41568043, 2025). "RT-qPCR results further depicted reduced expression levels of HDAC8 and SUCNR1 and enhanced IRF1 expression levels in the tumor tissues of mice treated with sh-HDAC8, whereas SUCNR1 expression levels were enhanced, and those of HDAC8 and IRF1 did not change after further oe-SUCNR1 treatment." (PMID 36035205, 2022). "Circulating succinate was elevated in patients with head and neck squamous cell carcinoma, along with increased expression of SUCNR1, HIF1α, SDHA and SDHB in the tumor tissue relative to matched normal mucosa, further highlighting a role of succinate as oncometabolite." (PMID 36551845, 2022). "Additionally, the expression of SUCNR1, HIF-1α, succinate dehydrogenase (SDH) A, and SDHB was higher in the tumor tissue than in the matched normal mucosa." (PMID 33916314, 2021).
tumor (continued). "In this study, we found that SUCNR1, C3aR1, C5aR1, MMP14, THBS 1, TSP-1, and TREM2, which are abnormally expressed in tumor tissue in situ, may be potentially associated with lymph node metastasis." (PMID 37744272, 2023).
cancer (38 papers, 2017 to 2026). A tumor composed of atypical neoplastic, often pleomorphic cells that invade other tissues. "Although extracellular succinate has not been directly linked to induction of mitochondrial fragmentation in cancer cells, a report on human mesenchymal stromal cells suggests that succinate promotes cell migration by a SUCNR-1-mediated Drp-1 phosphorylation." (PMID 36344992, 2022). "Our results showed that the association of SUCNR1 expression levels with varying populations of immune cells, microbiota, and immunomodulators may have influenced the outcome of the two cancers." (PMID 36551549, 2022). "Moreover, SUCNR1 is also linked to cancer and inflammatory pathologies." (PMID 36551549, 2022). "SUCNR1 is expressed in various tissues, including the kidney, liver, and adipose tissue, as well as in immune cells and cancer subtypes." (PMID 41994414, 2026). "In metabolic tissues and cancer, SUCNR1 coordinates adaptive responses to nutrient and oxygen stress while shaping the tissue microenvironment." (PMID 41994414, 2026). "Cancer cells were reported to release succinate into their microenvironment and activate succinate receptor (SUCNR1) signaling to polarize macrophages into TAM, promoting cancer cell migration, invasion, and metastasis." (PMID 41367876, 2025). "Succinate expelled by TAMs binds to succinate receptor 1 (SUCNR1) on cancer cells, triggering mitogenic signaling via the PI3K and ERK pathways." (PMID 40904700, 2025). "Activation of SUCNR1 has been reported in many cancer types and can activate several downstream pathways including Erk1/2, prostaglandin E2 (PGE2), p38 MAPK, Akt, and AMPK with various effects." (PMID 39796781, 2025). "Our previous findings that SUCNR1 knockdown increases mitochondrial respiration and ROS in Gln‐dependent cancer cells support this conclusion." (PMID 39838520, 2025). "Recent reports indicate that cancer‐secreted succinic enhances cancer cell migration and promotes cancer metastasis by activating succinate receptor‐1 (SUCNR‐1)‐mediated signaling and transcriptional pathways." (PMID 39584783, 2024). "SA increases the expression of succinate receptor-1 (SUCNR-1) in cancer cells, which is considered a target for the development of new anti-metastasis drugs." (PMID 38592508, 2024). "In this scenario, the importance of studying the effects of succinate and SUCNR1 not only in cancer cells, but also in TME, is highlighted." (PMID 37033265, 2023). "Succinate ́s favorable role to cancer progression seems clear and, actually, SUCNR1 overexpression has been identified in different tumor types, such as renal cancer." (PMID 37345199, 2023). "A high level of SUCNR-1 is expressed on cancer cells and its silencing by shRNA (short hairpin RNA) results in reducing cancer cell migration and invasion." (PMID 36344992, 2022). "Cancer cell-derived succinate activates SUCNR-1 resulting in ERK1/2 activation, prostaglandin E2 production and increased intracellular calcium." (PMID 36344992, 2022). "Succinate drives cancer cell migration and enhances cancer metastasis by interaction with SUCNR-1 on cancer cell surface." (PMID 36344992, 2022). "Recent reports indicate that cancer-secreted succinate enhances cancer cell migration and promotes cancer metastasis by activating succinate receptor-1 (SUCNR-1)-mediated signaling and transcription pathways." (PMID 36344992, 2022). "Extracellular succinate acts in an autocrine and paracrine manner to enhance cancer cell migration by activating a specific G-protein coupled receptor, SUCNR-1 which signals via ERK1/2 and PI-3 K/Akt." (PMID 36344992, 2022). "It has been reported that cancer cell SUCNR-1 expression is upregulated by extracellular succinate or SDH subunit silencing, indicative of a feedback regulation." (PMID 36344992, 2022). "Further studies are needed to develop therapeutic agents based on differential inhibition of SUCNR-1 on cancer metastasis vs. normal cellular physiological functions." (PMID 36344992, 2022).